IL13 (interleukin 13)
Diseases named in the same sentence as IL13 in open-access papers (continued):
Sharing a sentence is not in itself a finding about the gene and the disease.
mycobacterial infections (1 paper, 2018). "The concentrations of IL-13 and IL-1β were found to be significantly reduced in hospitalised cats when compared to both control cats and those with mycobacterial infections." (PMID 30470763, 2018).
mycosis fungoides (1 paper, 2024). Classical mycosis fungoides is the most common type of mycosis fungoides (MF), a form of cutaneous T-cell lymphoma, and is characterized by slow progression from patches to more infiltrated plaques and eventually to tumors. "This review analyzes current knowledge on the IL-4/IL-13 axis in mycosis fungoides and Sezary syndrome, the most common types of CTCL, examining existing literature on the pathogenetic implications with a focus on investigational treatments." (PMID 38398754, 2024).
myocardial disease (1 paper, 2017). "The role of IL‐4 and IL‐13 signaling in myocardial disease has been controversial." (PMID 28528324, 2017).
neuropathy (1 paper, 2025). A disorder affecting the nervous system that manifests with pain, tingling, numbness, and/or muscle weakness. "However, nerve cells can mitigate nerve damage and neuropathy by producing anti-inflammatory cytokines such as transforming growth factor-β (TGF-β), IL-4, IL-10, and IL-13." (PMID 40718454, 2025).
neuroschistosomiasis (1 paper, 2024). Schistosomiasis of the brain, spinal cord, or meninges caused by infections with trematodes of the genus schistosoma (primarily schistosoma japonicum; schistosoma mansoni; and schistosoma haematobium in humans). "In the present study, the predominant production of TNFα over type 2 cytokines (IL-4 and IL-13) could suggest the domination of pro-inflammatory effects of TNFα during neuroschistosomiasis after 8 weeks post-infections." (PMID 39959586, 2024).
neutrophilic disease (1 paper, 2021). "As such, this possibility cannot be entirely excluded but the data is more consistent with the peripheral airway IL‐13 being linked to neutrophilic disease." (PMID 33411348, 2021).
nicotine addiction (1 paper, 2026). "Future studies are needed to fully elucidate the role of IL-13/IL-13Rα1 signaling in the development of nicotine addiction and its possible translational relevance." (PMID 40775068, 2026). "Our results also suggest that the mode of IL-13 (or IL-4) production and release in the CNS may affect motivation and vulnerability to nicotine addiction." (PMID 40775068, 2026).
NK/T-cell lymphoma (1 paper, 2018). "Here, we aimed to explore the biological roles and potential mechanism of IL-13 and ABCC4 in multidrug resistance of NK/T-cell lymphoma." (PMID 30643796, 2018). "ELISA analysis was used to determine the level of serum IL-13 and immunohistochemical analysis was applied to detect the ABCC4 expression level in patients with human NK/T-cell lymphoma." (PMID 30643796, 2018). "Levels of serum IL-13 and ABCC4 expression were observed to be upregulated in patients with human NK/T-cell lymphoma." (PMID 30643796, 2018).
ocular cicatricial pemphigoid (1 paper, 2025). Ocular cicatricial pemphigoid (OCP) is a form of mucous membrane pemphigoid (a group of rare, chronic autoimmune disorders) that affects the eyes. "Recently, IL-13 was shown to be an important contributor to conjunctival fibrosis and inflammation in Ocular Cicatricial Pemphigoid." (PMID 40901133, 2025).
oral lichen planus (1 paper, 2022). Oral lichen planus is a chronic inflammatory oral condition of unknown aetiology characterized by T-cell-mediated chronic immune response and abnormal epithelial keratinization cycle. "Large proportions of the dermal macrophages of the AD-dogs showed TRPA1-IR; this evidence was consistent with the data provided in the buccal samples of human patients with oral lichen planus and in skin samples of IL-13–induced chronic AD in mice." (PMID 36187821, 2022).
osteitis (1 paper, 2021). "In the same study, a positive correlation was found between IL-13 and both the Global Osteitis Scoring Scale (GOSS) and in vitro mineralization by osteoblast." (PMID 33477617, 2021).
Pain (1 paper, 2021). An unpleasant sensory and emotional experience associated with actual or potential tissue damage, or described in terms of such damage. "Thus, it is possible that IL-13 possess endogenous analgesic functions, which are down-regulated in conditions of chronic neuropathic pain." (PMID 33522900, 2021).
pancreatic ductal carcinoma (1 paper, 2025). "detected high levels of IL-13 in pancreatic ductal carcinoma cells, while normal pancreatic cells did not contain IL-13." (PMID 40948749, 2025).
pemphigus vulgaris (1 paper, 2023). Pemphigus is a group of chronic autoimmune skin diseases characterized by blister formations on the outer layer of the skin and the mucous membranes. "In this regard, several case reports have shown that using dupilumab, a monoclonal antibody targeting IL-4 and IL-13, successfully resolves BP, in addition to pemphigus vulgaris." (PMID 36979421, 2023).
peripheral nerve injury (1 paper, 2025). Injury to a peripheral nerve. "Anti-inflammatory interleukins, such as IL-4, IL-10, and IL-13, play a critical role in enhancing the repair microenvironment following peripheral nerve injury." (PMID 41573554, 2025). "After nerve injury, IL-13 induces macrophages to produce IL-10, which in turn reduces the excitability and spontaneous activity of peripheral sensory neurons, facilitating the resolution of peripheral nerve injury." (PMID 41573554, 2025).
Periportal fibrosis (1 paper, 2021). The presence of fibrosis affecting the interlobular stroma of liver. "IL-13 levels in the supernatant of PBMCs cultures from patients also show a positive association with the presence and severity of periportal fibrosis." (PMID 33692784, 2021). "As has already been described in the literature, we found an increase of the Th2 cytokines IL-4, IL-5, and IL-13 in the group with periportal fibrosis." (PMID 33692784, 2021). "The present study demonstrates a greater production of IL-4, IL-5, and IL-13 by the lymphocytes of individuals with periportal fibrosis." (PMID 33692784, 2021).
placental insufficiency (1 paper, 2012). Failure of the placenta to deliver an adequate supply of nutrients and oxygen to the fetus. "The IL-12/IL-13 and IL-12/IL-10 ratios are significantly higher in IUGR with placental insufficiency when compared to normal pregnancy (P < 0.04 in both cases)." (PMID 22110537, 2012). "The IL-12/IL-13 and IL-12/IL-10 ratios are higher in IUGR with placental insufficiency, also suggestive of a stronger inflammatory skew in IUGR with placental insufficiency." (PMID 22110537, 2012). "On the other hand, the anti-inflammatory cytokine IL-13 is produced at lower levels by PBMC from IUGR without placental insufficiency (5.8 pg/mL ± 1) than by PBMC from normal pregnant controls (15.3 pg/mL ± 2.6) (P < 0.002)." (PMID 22110537, 2012). "Two of the ratios, IL-6/IL-13 (P < 0.006) and IL-8/IL-13 (P < 0.001), were significantly higher in IUGR without placental insufficiency compared to normal pregnancy." (PMID 22110537, 2012). "Indeed, the levels of the anti-inflammatory cytokine IL-13 are higher in normal pregnancy as compared to the IUGR group and to IUGR without placental insufficiency; we also observed a trend towards lower IL-13 levels in IUGR with placental insufficiency (P < 0.059)." (PMID 22110537, 2012).
pneumoconiosis (1 paper, 2011). An occupational lung disorder caused by inhalation of dust particles. "In the present study, we investigated the association between the potential functional polymorphisms in IL-4, IL-4R, and IL-13 and coal workers' pneumoconiosis (CWP) risk in a Chinese population." (PMID 21857939, 2011).
polyarticular JIA (1 paper, 2008). "The highest levels of IL8 and IL13 were observed in children with polyarticular JIA." (PMID 18507862, 2008).
postpartum hemorrhage (1 paper, 2024). Hemorrhage defined as a blood loss in excess of 500 mL after vaginal delivery or more than 1000 mL after a cesarean delivery. "Severe postpartum hemorrhage correlated with CRP, IL-13, and proteins of the IL-17 family." (PMID 39696496, 2024).
pulpitis (1 paper, 2021). Inflammation of the dental pulp. "On the other hand, IL-7 and IL-13 levels were significantly higher in normal pulp tissue when compared to reversible and irreversible pulpitis." (PMID 34299403, 2021).
Pyoderma (1 paper, 2026). Any manifestation of a skin disease associated with the production of pus. "In a murine pyoderma model, bentonite pre-treatment of S. pseudintermedius prevented lesion development, reduced bacterial burden, and downregulated cutaneous expression of TNFα, IL-1β, and IL-13, findings that were corroborated by histological improvements." (PMID 41576001, 2026).
rectal cancer (1 paper, 2016). A primary or metastatic malignant neoplasm that affects the rectum. "We sought to determine whether a polymorphism in the Interleukin 13 gene (IL13), 1112 C/T (rs1800925) predicts responsiveness to neoadjuvant chemoradiotherapy (neoCRT) and prognosis in Chinese Han patients with locally advanced rectal cancer (LARC)." (PMID 27167201, 2016).
Retinal atrophy (1 paper, 2024). A nonspecific term denoting wasting, especially as a result of degeneration, of the retinal pigment epithelium (RPE) and neurosensory retinal cells. "It has been evidenced that higher CSF levels of the anti-inflammatory molecule IL-13 may contrast synaptic alterations in MS and reduce retinal atrophy assessed with OCT." (PMID 38585351, 2024).
retinal ischemia (1 paper, 2024). A ischemic disease that involves the retina. "There appears to be a negative correlation between intraocular IL-12/IL-13 with retinal ischemia, CRT, and serous retinal detachment." (PMID 39272767, 2024).
Rett syndrome (1 paper, 2025). A severe neurodevelopmental disorder affecting the central nervous system. "For Rett syndrome (RTT), another uncharacterized and intractable disease without known targets, IL-13 was predicted as an inhibitory target." (PMID 39880378, 2025).
rhabdomyosarcoma (1 paper, 2021). A rare aggressive malignant mesenchymal neoplasm arising from skeletal muscle. "In rhabdomyosarcoma cells, IL4 and IL13 activate cellular proliferation through the JAK/STAT signaling pathway, and blocking IL4R with a neutralizing antibody suppressed tumor progression." (PMID 33419470, 2021).
rheumatic diseases (1 paper, 2024). "While IL-13’s exact role in rheumatic diseases is uncertain, it may influence their pathogenesis, especially in the production of autoantibodies such as rheumatoid factor (RF)." (PMID 38675400, 2024).
rheumatic heart disease (1 paper, 2021). An autoinflammatory condition following an infection with Group A Beta Hemolytic Streptococcus (GABHS), in which the heart is attacked by antibodies formed in reaction to a recent GABHS infection. "Consistently, the study in patients with rheumatic heart disease observed higher serum levels of IL‐13 and meanwhile increased local collagen deposition in valves, suggesting IL‐13 might induce fibrosis in rheumatic heart disease as well." (PMID 33943014, 2021).
scoliosis (1 paper, 2024). A congenital or acquired spinal deformity characterized by lateral curvature of the spine. "We found that levels of interleukin-13, osteoprotegerin, and tumor necrosis factor receptor superfamily member 9 were protective factors against scoliosis." (PMID 38875409, 2024).
scrub typhus (1 paper, 2023). Scrub typhus is a rare dust mite-borne infectious disease caused by the Orientia tsutsugamushi bacterium and characterized clinically by an eruptive fever which is potentially serious. "Ot infection can also slightly increase serum IL-5, IL-9, IL-13, and GM-CSF levels; however, their roles in scrub typhus remain unclear." (PMID 38091346, 2023).
selenium deficiency (1 paper, 2020). A nutritional deficiency disease resulting from inadequate selenium levels in the body, which can lead to impaired function of selenoproteins essential for antioxidant defense and thyroid hormone metabolism. "As IL-10, IL-13, IL-4, and IL-5 are part of Th2 responses, selenium deficiency may have induced more Th2 responses than Th1 responses in the lungs of mice infected with influenza virus." (PMID 33207753, 2020). "Selenium deficiency decreased the mRNA expression of IFN-γ and IL-2, but increased the mRNA expression of IL-10, IL-13, IL-4, and IL-5 in the mediastinal lymph nodes." (PMID 33207753, 2020).
seminoma (1 paper, 2022). A radiosensitive malignant germ cell tumor found in the testis (especially undescended), and extragonadal sites (anterior mediastinum and pineal gland). "We identified all proteins secreted by seminoma (TCam‐2), EC (2102EP and NCCIT), choriocarcinoma (JAR and JEG‐3), and yolk‐sac tumor cell lines (GCT72) as well as fibroblasts (MPAF and HVHF2), endothelial cells (HUVEC), MIL4/IL13 macrophages (THP‐1‐ MIL4/IL13) and T‐lymphocytes (JURKAT)." (PMID 35811571, 2022).
Sertoli Cell-Only Syndrome (1 paper, 2023). A type of male infertility in which no germ cells are visible in any of the biopsied SEMINIFEROUS TUBULES (type I) or in which germ cells are present in a minority of tubules (type II). "So, when the spermatogenic dysfunction happens (especially in Sertoli-cell-only syndrome and early spermatogenic arrest), the decrease of IL13 in the microenvironment is most likely due to the decrease of germ cell numbers, rather than the decrease of secretion amount per cell." (PMID 37221631, 2023).
sinus disorders (1 paper, 2006). "The CRS-FA patients in this study showed an aberrant Th2 pattern immune reaction as high levels of serum antigen specific IgE, IL-4, IL-13 and low levels of IFN-γ were recorded before the treatment of their sinus disorders." (PMID 16919166, 2006).
skin sensitization (1 paper, 2025). An immunological response to previous exposure to a substance which results in an inflammatory skin reaction. "IL-13 signaling in dendritic cells selectively contributes to the skin sensitization-mediated IgE responses." (PMID 39989951, 2025). "In the context of skin sensitization, dermal DCs and/or CX3CR1 DCs play a role in allergen delivery to LNs and spleen, and IL-13 has a selective role in providing the activation signal for cDC2s to increase antigen-presenting capacity and promote robust IgE responses via memory Th2 and TFH2 cells." (PMID 39989951, 2025).
skin tumour (1 paper, 2016). "We assessed skin tumour formation in IL-13-deficient mice using two different models of spontaneous epithelial carcinogenesis." (PMID 27357235, 2016).
smallpox (1 paper, 2011). A condition that is caused by infection with Variola, and that is characterized by small, raised bumps. "The results presented here show that human vaccinia specific CD4+ T cell clones that emerge following smallpox vaccination produce high levels of IL-13 in response to vaccinia and peptide stimulation." (PMID 21931646, 2011). "In addition, it has been shown that following smallpox immunization a small proportion of vaccinia specific CD4+ T cells produce exclusively IL-13 during the peak effector phase of the response (2 weeks following Dryvax vaccination)." (PMID 21931646, 2011).
spinal cord ischemia (1 paper, 2021). Reduced blood flow to the spinal cord which is supplied by the anterior spinal artery and the paired posterior spinal arteries. "Additionally, some studies showed that IL-4 and IL-13 suppressed the expression and production of pro-inflammatory cytokines (TNF-α and IL-1β) in the spinal cord of animal models of spinal cord ischemia." (PMID 34679060, 2021).
staphylococcus aureus infection (1 paper, 2025). An infectious process in which the bacteria Staphylococcus aureus is present. "The KEGG pathways associated with AD were mainly involved in the IL-10 signaling pathway, IL-4 and IL-13 signaling, TGF-beta receptor signaling, the TCR pathway during Staphylococcus aureus infection signaling, and the STAT3 pathways." (PMID 41471858, 2025).
streptococcus infection (1 paper, 2022). "In the present study, the IL-13 concentration increased within 24 h following the onset of inflammation caused by streptococcus infection." (PMID 35733860, 2022).
TB meningitis (1 paper, 2022). "This diagnostic assay uses VEGF, IL-13, and cathelicidin LL-37 to detect TB meningitis in children." (PMID 36010011, 2022).
thrombotic microangiopathy (1 paper, 2015). The syndromes of microangiopathic hemolytic anemia, thrombocytopenia, and variable signs of organ impairment, due to platelet aggregation in the microcirculation. "The first two patients treated with 2 μg/kg of IL-13-PE developed Grade 3 and 4 toxicities most consistent with thrombotic microangiopathy but only required supportive care." (PMID 25767039, 2015).
thymic carcinoma (1 paper, 2025). Thymic carcinoma (TC) is a type of thymic epithelial neoplasm characterized by a high malignant potential. "Unexpectedly, thymic carcinoma cases exhibited a distinct cytokine milieu skewed toward type 2 inflammation, with increased levels of IL-4, IL-5, IL-9, and IL-13." (PMID 41368637, 2025). "Serum IL-18 levels were elevated—particularly in thymic carcinoma—and correlated with higher concentrations of type 2 cytokines (IL-4, IL-5, IL-9, IL-13)." (PMID 41368637, 2025).
thyroid cancer (1 paper, 2021). "Likewise, M2-like tumor-associated macrophages polarized by IL-4/IL-13 promote stemness and metastasis of thyroid cancer cells by secreting IGF-I and IGF-II." (PMID 34769439, 2021).
thyroid disease (1 paper, 2020). "Serum level of IL-6, IL-7, IL-10, and IL-13 was higher in thyroid disease, while IL-8 was lower than healthy controls." (PMID 32655554, 2020). "It is reported that the combination of IL-13 and IL-8 is highly efficient in identify thyroid diseases (AUC 0.90)." (PMID 32655554, 2020). "Serum levels of IL-7, IL-10, and IL-13 are higher in thyroid diseases than healthy controls." (PMID 32655554, 2020).
tongue tumors (1 paper, 2013). "The mice given the IL-13-PE therapy had roughly the same occurrence of tongue tumors as the controls, so the immunotoxin treatment most likely delayed the development of these tumors, which accounts for the increased survival." (PMID 23421960, 2013). "The untreated mice exhibited weight loss, particularly with the rapid onset of tongue tumors, but the treated mice gained weight while on IL-13-PE therapy and showed no clinical signs of toxicity due to the immunotoxin." (PMID 23421960, 2013). "Unlike the controls, the mice treated with the IL-13-PE group did not experience the immediate weight loss that typically occurs during tongue tumor development due to obstructed eating." (PMID 23421960, 2013).
toxic epidermal necrolysis (1 paper, 2025). Toxic epidermal necrolysis (TEN) is an acute and severe skin disease with clinical and histological features characterized by the destruction and detachment of the skin epithelium and mucous membranes. "Severe cutaneous adverse reactions, including DRESS, SJS, and toxic epidermal necrolysis (TEN), involve pathogenic mechanisms in which cytotoxic CD8+ T lymphocytes, as well as certain pro-inflammatory eosinophil promoting cytokines (such as IL-4, IL-5, IL-9, IL-13), play a role." (PMID 40869188, 2025).
Trichinella spiralis infection (1 paper, 2019). "IL-13 induces goblet cell proliferation during Trichinella spiralis infection, and treatment with IL-13 secreting cells results in increased Alcian blue staining of acidic mucins in tissue of mice with asthmatic airway inflammation." (PMID 30665337, 2019).
triple-negative breast carcinoma (1 paper, 2024). An invasive breast carcinoma which is negative for expression of estrogen receptor (ER), progesterone receptor (PR), and human epidermal growth factor receptor 2 (HER2). "In mouse tumor models, innate lymphoid cells promoted triple-negative breast cancer (TNBC) lung metastasis through the IL-13 axis, whereas IL-13 blockade delayed pro-tumor TIME establishment." (PMID 38649887, 2024).